TLR4 (toll like receptor 4)
Diseases named in the same sentence as TLR4 in open-access papers (continued):
Sharing a sentence is not in itself a finding about the gene and the disease.
alcohol abuse (22 papers, 2013 to 2025). The use of alcoholic beverages to excess, either on individual occasions ("binge drinking") or as a regular practice. "TLRs implicated in alcohol abuse such as TLR4 and TLR7 undergo a developmental downregulation across adolescence." (PMID 35559229, 2022). "The functional enrichment of the miR-183C and miR-200a/b family target genes revealed that neuroinflammatory pathways networks are involved in TLR4 signaling associated with alcohol abuse." (PMID 32780740, 2020). "We evaluated the role of miRNAs as potential modulators of the neuroinflammation associated with alcohol abuse and the influence of the TLR4 response." (PMID 30374194, 2018). "We further present enriched GO and KEGG functional networks analyses that open up possible new therapeutically gene targets to prevent the deleterious effects of alcohol abuse linked to the TLR4 immune response in the brain." (PMID 30374194, 2018). "The changes in the neuroinflammatory targets genes associated with alcohol abuse were mostly abolished in the TLR4-KO mice." (PMID 30374194, 2018). "However, repeated alcohol intoxication such as chronic alcohol abuse abolishes the initial anti-inflammatory effect and leads to the loss of TLR4 tolerance, supporting the theory about the biphasic effect of alcohol." (PMID 34084163, 2021). "However, changes in the neuroinflammatory target genes associated with alcohol abuse were abolished mostly in the ethanol-treated TLR4-KO mice." (PMID 32780740, 2020). "Alcohol abuse activates TLR4-related signaling pathways, leading to systemic inflammation and increased TNF-α production." (PMID 41194914, 2025). "Conversely, alcohol abuse induces a TLR4-dependent inflammatory response, leading to dysbiosis and gut barrier disruption." (PMID 39684246, 2024). "We selected Toll-like Receptor 7/8 (TLR 7/8) because these receptors have been related to TLR4 pathways and alcohol abuse." (PMID 32780740, 2020). "Functional enrichment of the miR-183C and miR-200a/b family target genes, revealed neuroinflammatory pathways networks involved in TLR4 signaling and alcohol abuse." (PMID 30374194, 2018). "We next performed a complementary analysis to further establish the main biological functions and key pathways involved in alcohol abuse, TLR4 immune response and miR-183C/miR-200s family." (PMID 30374194, 2018). "We next assessed the potential genes/proteins targeted by miR-183C and miR-200a/b that were involved in the effects of alcohol abuse and TLR4 immune response." (PMID 30374194, 2018). "The transformation of these progenitor cells to HCC is driven by the TLR4 signaling pathway, which is upregulated by increases in LPS levels in the liver that result from alcohol abuse." (PMID 24313165, 2013). "Likewise, liver injury inflicted by alcohol abuse also exaggerates EV release, carrying inflammatory signaling molecules (NFκB, TLR4, IL-1 receptors, caspase-1) into the circulation." (PMID 38014253, 2023). "Specifically, increased gut permeability due to alcohol abuse leads to elevated levels of lipopolysaccharide (LPS) in the portal blood flow that binds to TLR4 and activates NF-κB, subsequently stimulating pro-inflammatory cytokine release, ROS production, and oxidative stress." (PMID 35959296, 2022). "Alcohol abuse induces brain neurodegeneration resulting in elevation of proinflammatory cytokines and chemokines expression and, in particular, microglia can be activated through their receptors (such as Toll-like receptor 4)." (PMID 35335908, 2022). "Consequently, we found that chronic alcohol abuse increased the expression of these genes in WT mice cortices, with minor changes in TLR4-KO compared with the untreated control mice." (PMID 30374194, 2018).
alcohol abuse (continued). "Alcohol abuse triggers peripheral inflammation and central neuroinflammation; the receptor-mediated enabler of this diffuse inflammatory response is the upregulation of the innate immunity TLR4 (Toll-Like Receptor 4) protein with subsequent microglial and inflammatory cytokine involvement." (PMID 38248256, 2023). "The present findings demonstrated that chronic alcohol abuse modified the expression of genes ITLN1 and CFTR in WT mice intestines with minor changes in TLR4-KO compared to the untreated control mice." (PMID 34884634, 2021).
cognitive decline (22 papers, 2013 to 2025). "The TREM2 R47H gene variant is associated with changes in cognitive decline in HD patients, and rs1927911 and rs10116253 TLR4 single nucleotide polymorphisms are associated with the rate of motor decline." (PMID 38459557, 2024). "TLR4-mut mice fed both the HFD and ND performed similarly in both tasks, indicating that the TLR4 mutation protected animals from MS-associated cognitive decline." (PMID 35488354, 2022). "We found that TREM2 rs1927911 was associated with the rate of cognitive decline, whereas TLR4 rs1927911 and TLR4 rs1927914 were both associated with the rate of motor decline." (PMID 31724242, 2020). "We also found that the TREM2 R47H gene variant was associated with changes in cognitive decline in the large cohort of HD patients, whereas 2 of 3 TLR4 single nucleotide polymorphisms assessed were associated with changes in motor progression in this same group." (PMID 31724242, 2020). "We further examined the relationship between cognitive function and whole-brain average as well as individual regional FA to explore whether cognitive decline caused by TLR4/NF-κB signaling activation is due to specific white matter defects or if other brain structures are also involved." (PMID 36051545, 2022). "TNC interacts with TLR4 to enhance immune and inflammatory responses, contributing to the progression and cognitive decline in chronic conditions such as AD and PD." (PMID 41155465, 2025). "The engagement of TLR4 signaling cascades in AD pathophysiology demonstrates concurrent involvement in neuroinflammatory processes and cognitive decline." (PMID 41155465, 2025). "The positive effects are involved in the participation of the irisin/TLR4/MyD88/NF-κB signaling pathway, highlighting the potential of exercise in the management of diabetic-induced cognitive decline." (PMID 39452118, 2024). "Neutralizing each of these targets (Aβ, RAGE, S100A9, and TLR4) individually has been shown to slow cognitive decline in animal models." (PMID 36291595, 2022). "Recently, TLR4 was also identified as a modulator of neurogenesis in the brain during injuries, cerebral ischemia, and cognitive decline, and it is recognized to contribute to neuroplasticity." (PMID 32059688, 2020). "Studies have reported that TLR4 in the central nervous system (CNS) involved in memory, learning impairment and cognitive decline." (PMID 32059688, 2020). "Conversely, TLR4 KO can counteract the B2M-induced cognitive decline due to neuroinflammation and apoptosis via a modulation of hippocmapal neurogenesis, synaptic plasticity through TLR4/MyD88/NF-κB signaling pathway." (PMID 32059688, 2020). "Mice exposed to sevoflurane demonstrate increased proinflammatory cytokines production and TLR4‐NF‐κB signaling activation, and TLR4 deletion could protect aged mice from sevoflurane‐induced cognitive decline along with suppressed cytokine production." (PMID 36573756, 2023). "Our data suggest that TLR4 signaling activation is involved in microvascular dysfunction and neuroinflammation associated with HFD-induced MS and that this receptor possibly plays a causative role in the development of cognitive decline." (PMID 35488354, 2022). "Our results demonstrate that TLR4 is involved in the microvascular dysfunction and neuroinflammation associated with HFD-induced MS and possibly has a causal role in the development of cognitive decline." (PMID 35488354, 2022). "Aβ, RAGE, S100A9, and TLR4 play important roles in AD pathogenesis by orchestrating the feed-forward mechanism between neuroinflammation and neurodegeneration, two pathways driving the cognitive decline in AD." (PMID 36291595, 2022). "Toll-like receptor 4 (TLR4) is a crucial receptor in neuroinflammation and apoptotic neuronal death, and increasing evidences indicated that β2-microglobulin (B2M) is thought to be a major contributor to age-related cognitive decline." (PMID 32059688, 2020).
cognitive decline (continued). "In the present study, we found that B2M increased TLR4 mRNA expression in the hippocampus of WT mice for the first time, demonstrating TLR4 may be an important pathway for B2M to be a participant in age-related cognitive decline." (PMID 32059688, 2020). "In our study, the histamine 2/3 receptor agonists inhibited exploratory laparotomy- or LPS-induced cognitive decline, microglia activation, proinflammatory cytokine production, NF-κb expression, M1/M2 phenotype transformation, cell migration, and TLR4 expression through the PI3K/AKT/FoxO1 pathway." (PMID 32698899, 2020). "Our previous studies found that microglia activation participate in the surgery-induced neuroinflammation and cognitive decline through TLR4/MyD88 signaling, which can be improved by preintraperitoneal injection of lithium for continuous 6 days before splenectomy." (PMID 27245661, 2016). "β2M could induce cognitive decline via neuroinflammation through toll-like receptor 4 (TLR4)." (PMID 37773139, 2023). "The impact of this complex process, which includes the alteration of the TLR4 pathway and glial activation among other processes, induces the release of pro-inflammatory cytokines and aberrant neuronal circuits, contributing altogether to the acceleration of cognitive decline." (PMID 35899125, 2022). "Furthermore, evaluating the local modulation of TLR4 would be an interesting pharmacological approach to prevent or treat cognitive decline in MS and could be the subject of future studies." (PMID 35488354, 2022). "In support of this notion, genetic knockout of Tlr4 does not prevent cognitive decline in mice receiving orthopedic surgery." (PMID 31660984, 2019). "First, initiation of B2M treatment may represent a limitation because the half time of drugs, and measurement indicators levels were not fully rescued in TLR4 KO mice, other factors affected the B2M-induced cognitive decline should be researched in the future." (PMID 32059688, 2020).
liver cirrhosis (22 papers, 2012 to 2025). "Interfering with ANGPTL4 through the TLR4/NF-κB pathway can inhibit fibrosis in hepatic stellate cells and impede the progression of liver cirrhosis in mice." (PMID 38992710, 2024). "Given the role of TLR4 activation and the downstream adapter MyD88 in activating the NF-κB signaling pathway, we investigated the influences of liver cirrhosis on TLR4/MyD88/NF-κB signaling in ileum tissues using RT-PCR and Western blot analysis." (PMID 37273916, 2023). "In this study, we revealed that vitamin D suppressed liver cirrhosis-induced intestinal inflammation and oxidative stress through the TLR4/MyD88/NF-κB pathway." (PMID 37273916, 2023). "Conversely, rats received low-dose or high-dose treatment of vitamin D exhibited decreased expression levels of TLR4, MyD88, and phospho-NF-κB p65 (p-NF-κB) in the ileum tissues compared with the liver cirrhosis model group." (PMID 37273916, 2023). "In this study, we found the activation of TLR4/MyD88/NF-κB pathway in intestinal tissues of liver cirrhosis rats while the treatment of vitamin D remarkably suppressed the TLR4/MyD88/NF-κB pathway." (PMID 37273916, 2023). "The results showed that liver cirrhosis activated TLR4/MyD88/NF-κB signaling in ileum samples of rats compared with the control group." (PMID 37273916, 2023). "Taurine-conjugated bile acids have been shown to promote liver cirrhosis via upregulating Toll-like receptor 4 expression, and to increase intestinal permeability and render dysfunction of the intestinal barrier." (PMID 34071196, 2021). "Lipopolysaccharide (LPS) or endotoxin promotes systemic inflammation by activating TLR-2 and TLR-4 dependent pathways and promoting cytokines in large quantities, thereby accelerating the progression of liver cirrhosis." (PMID 34712665, 2021). "Wistar rats with thioacetamide-induced liver cirrhosis had low expression of TLR4 and reduced liver damage when supplemented with Lactobacillus (L.) plantarum probiotic bacteria." (PMID 33807605, 2021). "The mechanisms of TCA promoting liver cirrhosis are likely through activating hepatic stellate cell via TLR4 pathways." (PMID 29996772, 2018). "TCA promoting liver cirrhosis is likely through activating hepatic stellate cells via upregulating TLR4 expression." (PMID 29996772, 2018). "Molecular epidemiology studies have revealed that polymorphisms of TLR4 gene (T399I and D299G) can affect the susceptibility of HCV infected patients to develop liver cirrhosis." (PMID 29996772, 2018). "Although both LPS and TLR4 has an important role in liver cirrhosis, the mechanism is still unclear." (PMID 22927965, 2012). "Mechanistically, vitamin D might promote the process of liver cirrhosis-induced intestinal damage repair by suppressing the TLR4/MyD88/NF-κB signaling pathway." (PMID 37273916, 2023). "The reactivity is significantly weakened in the presence of TLR4 blockers, indicating that LPS may activate platelets through TLR4 and may lead to liver cirrhosis-related thrombotic complications." (PMID 38293307, 2023). "Moreover, vitamin D effectively inhibited liver cirrhosis-induced intestinal inflammation and oxidative stress through the TLR4/MyD88/NF-κB pathway." (PMID 37273916, 2023). "TLR4 signaling pathway plays an important role in the development of liver cirrhosis." (PMID 29996772, 2018). "Additionally, TLR4 signaling pathway orchestrates with increased intestinal permeability in liver cirrhosis." (PMID 29996772, 2018). "Finally, we used subcutaneous injection to induce local and systemic inflammation because of the higher toxicity of lipopolysaccharides (pure ligands of TLR-4), which induced liver cirrhosis when administered for 3 months." (PMID 24901254, 2014). "Also, down-regulation of TLR4 has been related to liver cirrhosis." (PMID 28032149, 2017).
liver cirrhosis (continued). "CXCL9 is known to promote the HCC invasion through PREX-2, therefore downregulation of the TLR4 and CXCL9/PREX-2 by probiotic bacteria could suppress the development of liver cirrhosis in the thioacetamide-treated rat model." (PMID 33807605, 2021). "Patients with acute deterioration of liver cirrhosis and non-HRS renal dysfunction and inflammation with coexisting tubular damage have higher values of urinary TLR4, which suggests a potential role of TLR4 in renal injury pathophysiology and indicates the potential role of ATN-AKI as a biomarker." (PMID 38139297, 2023).
urinary tract infection (22 papers, 2010 to 2025). "Our results suggest a causative role of the TLR4 Asp299Gly polymorphism in the occurrence and progression of UTIs in children of Greek origin while, on the contrary, a protective role of the TLR4 Thr399Ile polymorphism against urinary tract infections." (PMID 31183391, 2019). "Heightened susceptibility to urinary tract infections (UTIs), asymptomatic and persistent bacteriuria have been associated to low levels of TLR4 expression and TLR4 polymorphisms in human being." (PMID 25161655, 2014). "Since TLR4 plays a vital role in susceptibility to urinary tract infection (UTI), promoter sequences were obtained from children with mild or severe disease." (PMID 20505764, 2010). "It seems that activation of the CD14/TLR2 and/or CD14/TLR4 pathway during the acute phase, which reflects the general activation of the immune system due to the underlying infection, may play an important role in the limitation of urinary tract infection." (PMID 27252945, 2016). "The presence of TLR4 on the surface of the urothelium and immune cells is essential in order to combat the development of urinary tract infections." (PMID 36983379, 2023). "Strains from the environment or adapted to laboratory, as well as clinical isolates from bloodstream or urinary tract infections, typically express penta-acylated LPS with low TLR4 agonist activity." (PMID 31214180, 2019). "As a key component of the innate immunity, Pentraxin 3 activated the downstream TLR4-MyD88 pathway during urinary tract infection." (PMID 27409608, 2016). "Notably, FimH is a particularly promising vaccine candidate, as it has already progressed to phase II clinical trials for the prevention of recurrent urinary tract infections, utilizing a TLR4 agonist as an adjuvant." (PMID 40854638, 2025). "Furthermore, the uropathogenic E. coli (UPEC) triggers innate responses during urinary tract infection in a TLR4-dependent and CD14-independent manner both in mice and humans." (PMID 23166489, 2012). "Of these, the most studied receptors with a role in the pathophysiology of urinary tract infections are TLR2, TLR4, and TLR5 in humans and TLR 11 in murine models." (PMID 36983379, 2023). "In a murine urinary tract infection (UTI) model, lipopolysaccharide of uropathogenic E. coli and its receptor TLR4 are required for post-UTI chronic pain development." (PMID 29739958, 2018). "C3H/HeJ mice without response to LPS (TLR4 mutant mice) couldn't clear the urinary tract infection." (PMID 21151974, 2010).